IL6 (interleukin 6)
Diseases named in the same sentence as IL6 in open-access papers (continued):
Sharing a sentence is not in itself a finding about the gene and the disease.
dysentery (5 papers, 2008 to 2024). Acute inflammation of the intestine associated with infectious diarrhea of various etiologies, generally acquired by eating contaminated food containing toxins, biological derived from bacteria or other microorganisms. "TNF-α increased in all animals after inoculation, with a peak during dysentery, and IL-6 was found in 3 animals during dysentery and in the 2 animals that did not develop clinical signs of disease." (PMID 18700003, 2008). "Blood was sampled before inoculation and repeatedly during acute dysentery and recovery periods and cytokine levels of IL-1β, IL-6, Il-10, TNF-α and IFN-γ were measured by ELISA." (PMID 18700003, 2008). "The aim of the present study was therefore to induce dysentery experimentally in pigs and to monitor the development of some immunoregulatory cytokines (IL-1β, IL-6, Il-10, TNF-α and IFN-γ) in blood collected at various stages of the disease." (PMID 18700003, 2008). "In the present study it seemed that serum IL-6 was not a reliable marker of swine dysentery, as only three of the sick animals showed detectable levels of this cytokine in the blood during dysentery." (PMID 18700003, 2008).
dyspepsia (5 papers, 2016 to 2025). An uncomfortable, often painful feeling in the stomach, resulting from impaired digestion. "Preclinical studies reveal that activation of the NF-κB signaling pathway and increased interleukin-6 (IL-6) levels in the duodenal mucosa characterize dyspepsia model rats, indicative of mucosal inflammation." (PMID 40171499, 2025). "A study in H. pylori-positive patients with functional dyspepsia investigated gastric inflammatory markers and ILs (IL-4, IL-6, IL-8, IL-10, and IFN-γ) following treatment with AXT from H. pluvialis." (PMID 31248010, 2019).
enterovirus infection (5 papers, 2013 to 2025). "Enteroviral infection can induce cytokine storm in a variety of tissues, which is characterized by marked upregulation of key inflammatory mediators, including cytokines (e.g., IL-6, TNF-α), chemokines (e.g., MCP-1), and COX-2, etc.." (PMID 41300404, 2025). "Aside from virucidal activity and attachment inhibition, eupafolin significantly inhibited production of IL-6 and RANTES in enterovirus infection." (PMID 24078828, 2013).
frontotemporal dementia (5 papers, 2015 to 2025). Frontotemporal dementia (FTD) comprises a group of neurodegenerative disorders, characterized by progressive changes in behavior, executive dysfunction and language impairment, as a result of degeneration of the medial prefrontal and frontoinsular cortices. "However, IL-6 plasma levels have also beenpreviously linked to disinhibition in frontotemporal dementia (FTD), apathy in AD, and manic symptoms inbipolar disorder." (PMID 40666430, 2025). "For example, a previous study reported that serum and cerebrospinal fluid (CSF) IL-6 levels did not change significantly in patients who developed frontotemporal lobar degeneration compared with controls." (PMID 37480061, 2023). "In frontotemporal dementia (FTD), patients with disinhibition had higher levels of plasma IL-6 compared to patients without disinhibition." (PMID 38336728, 2024).
generalized epilepsy (5 papers, 2018 to 2025). Epilepsy that is characterized by generalized seizure types and may have typical interictal and/or ictal EEG findings that accompany generalized seizure types (for example generalized spike-wave). "In vivo, IVIg infusion can induce IL-6 and IFN-γ in plasma of patients with secondary generalized epilepsy." (PMID 29617422, 2018). "A clinical study of 21 generalized epilepsy patients revealed that VPA treatment for 4–6 months decreased the serum level of IL-6 but not that of IL-1β or TNF-α." (PMID 40806813, 2025). "The aim of this study was the investigation of TNF-α, IL-10, IL-6, and IL-1β cytokines secretion in PBMC supernatants isolated from children affected by generalized epilepsy and treated in vitro with myofibrillar, sarcoplasmic, and total protein fractions of meat and fish sources." (PMID 35684043, 2022).
gingival overgrowth (5 papers, 2019 to 2025). Excessive growth of the gingiva either by an increase in the size of the constituent cells (gingival hypertrophy) or by an increase in their number (gingival hyperplasia). "Indeed, it has been amply demonstrated that the upregulation of salivary concentrations of proinflammatory cytokines such as interleukin (IL) 1α, IL-8, and IL-6 is implicated in the pathogenesis of cyclosporine-induced gingival overgrowth." (PMID 31438651, 2019). "As a result, phenytoin-induced gingival overgrowth is likely attributed to increased production of IL-6 and IL-8, in conjunction with elevated basic fibroblast growth factor (FGF)." (PMID 40115275, 2025). "In order to investigate the impact of the inflammatory component in the pathogenesis of amlodipine-induced gingival enlargement, we examined the relative gene expression of IL-6 and TNF-α." (PMID 39204180, 2024). "Specifically, IL-6 and TNF-α expression levels were lower in patients taking amlodipine compared to those with gingival enlargement who were not taking amlodipine." (PMID 39204180, 2024). "IL-6, TNF-α, ST2, and FGF-2 expression levels were lower in patients taking amlodipine, with and without gingival enlargement." (PMID 39204180, 2024).
Helicobacter infection (5 papers, 2013 to 2025). "Helicobacter infection promoted ROS generation, which elevated IL-6 production and subsequent STAT3 phosphorylation in AGS cells." (PMID 40264171, 2025). "Therefore in contrast to gp130-mediated antral tumors driven by the IL-6 family member IL-11, we show here that Helicobacter infection drives IL-6 expression and SPEM." (PMID 23520544, 2013). "The analysis of the most prominent pro-inflammatory cytokines involved in Helicobacter infection (IL8, IL6, TNFα, IL1β and IFNγ) revealed that the main difference between the two conditioned media was on IFNγ, not expressed in the THP1 system." (PMID 36514982, 2022). "In order to characterize the inflammatory response across the infection, we analyzed the levels of IL-1β, IL-6, IFN-γ, CXCL5, and CXCL15, reported to be up-regulated upon Helicobacter infection in different studies." (PMID 29085807, 2017).
Hematuria (5 papers, 2010 to 2022). The presence of blood in the urine. "Intake of MOF significantly reduced the incidence of post-race hematuria (p = 0.0004) and lowered concentrations of interleukin (IL)-6 in the urine (p = 0.032)." (PMID 32492913, 2020). "This suggests that urinary IL-6 reflects the severity and changes of pure renal hematuria, providing a reference for the clinical diagnosis of asymptomatic hematuria." (PMID 24137196, 2013). "In summary, urinary IL-6 and glomerular damage score were positively correlated in the pure renal hematuria group, suggesting that urinary IL-6 may reflect the severity degree and changes of pure renal hematuria, providing a diagnostic reference for the identification of asymptomatic hematuria." (PMID 24137196, 2013). "Serum IgA, IgA immune complexes, kidney mesangial IgA and hematuria were significantly higher in DON-fed wild-type mice than toxin-fed IL-6 KO suggesting that IL-6 is a requisite cytokine for DON-induced IgA production and resultant IgAN." (PMID 22069639, 2010). "Therefore, in the current study, patients with renal hematuria were selected for the observation of urinary IL-6 levels and further investigation of the correlation between urinary IL-6 levels and hematuria disease severity and changes." (PMID 24137196, 2013).
Hepatosplenomegaly (5 papers, 2009 to 2026). Simultaneous enlargement of the liver and spleen. "The circulating levels of IL-6 and IL-5 were found to have statistically significant relationships with hepatosplenomegaly, but in a non-linear fashion." (PMID 19149774, 2009).
hip osteoarthritis (5 papers, 2017 to 2025). "Recently, polymorphisms in both TGFB1 and IL-6 have been identified as being significantly associated with hip osteoarthritis in Caucasians." (PMID 28860542, 2017). "Neopterin may provide more reliable information regarding inflammatory status of a patient by being more sensitive than CRP or IL-6, which have not been able to distinguish between knee and hip osteoarthritis or subsequent arthroplasty surgery." (PMID 34403444, 2021).
Hypervolemia (5 papers, 2010 to 2025). An increase in the amount of intravascular fluid, particularly in the volume of the circulating blood. "To confirm that hypervolemia is linked to an inflammatory state in immune cells, we decided to determine IL-6." (PMID 38612530, 2024). "Furthermore, hypervolemia was associated with alveolar and endothelium damage as well as increased IL-6, VCAM-1 and ICAM-1 mRNA expressions in lung tissue; 2) RMs reduced alveolar collapse regardless of volemic status." (PMID 20546573, 2010). "We observed that: 1) hypervolemia increased lung W/D ratio with impairment of oxygenation and Est,L, and was associated with alveolar and endothelial cell damage and increased IL-6, VCAM-1, and ICAM-1 mRNA expressions; and 2) RM reduced alveolar collapse independent of volemic status." (PMID 20546573, 2010). "Furthermore, hypervolemia was associated with alveolar and endothelium damage as well as increased mRNA expression of IL-6, VCAM-1 and ICAM-1 in lung tissue." (PMID 20546573, 2010). "How far miR-142-3p expression affects IL-6 and IL-10 regulation in hypervolemia is the subject of future studies." (PMID 38612530, 2024). "The concentration of HA was trended over time, compared between groups, and studied for associations with the cumulative volume of intravenous fluids administered, a pro-inflammatory cytokine (interleukin-6, IL-6), and a biomarker of hypervolemia (atrial natriuretic peptide, ANP)." (PMID 40512747, 2025). "At the protein level, the proinflammatory cytokine IL-6 was significantly elevated in hypervolemia." (PMID 32138278, 2020). "In hypervolemia, we observed an increase in IL-6 mRNA expression in lung tissue, but PCIII mRNA expression did not change, which may be explained by the absence of hyperinflation." (PMID 20546573, 2010). "A secondary objective was to investigate the association of HA with the cumulative volume of IV fluids administered and with biomarkers of hypervolemia (ANP) and inflammation (IL-6)." (PMID 40512747, 2025). "Regarding the inflammatory nature exerted by hypervolemia in HD, we examined the mRNA expression of proinflammatory genes TNF-α and IL-6 in PBMCs." (PMID 38139378, 2023).
hypoparathyroidism (5 papers, 2020 to 2023). Hypoparathyroidism is an endocrine disorder in which the parathyroid glands in the neck do not produce enough parathyroid hormone (PTH). "Of note, inflammatory cytokines, including IL-6, have been described to increase the parathyroid calcium-sensing receptor (CaSR), which reduces parathyroid hormone (PTH) secretion, resulting in inflammation-associated hypocalcemic hypoparathyroidism." (PMID 36233666, 2022). "Cytokines, notably interleukin (IL)-1β and IL-6, lead to an upregulation of calcium-sensing receptor (CaSR) on parathyroid glands, increasing the sensitivity of the parathyroid cells to circulating calcium, resulting in a state of acquired relative hypoparathyroidism." (PMID 33490095, 2020).
Intellectual disability (5 papers, 2017 to 2024). "According to Heuer at al., the increased levels of IL-6 and IL-8 were associated with a global ASD phenotype when compared with TD, but only IL-8 was correlated with both the presence and the absence of intellectual disability." (PMID 32992922, 2020).
Intraventricular hemorrhage (5 papers, 2017 to 2025). Bleeding into the ventricles of the brain. "Elevated levels of IL-1β, IL-6, IL-8, and IL-10 in umbilical cord blood and early postnatal blood are associated with intraventricular hemorrhage and white matter lesions shortly after birth." (PMID 39857702, 2025). "For example, increased plasma IL-6 in preterm neonates is an independent risk factor for intraventricular haemorrhage and periventricular leukomalacia during the early postnatal period." (PMID 37936886, 2023). "The researchers demonstrated that the factors that predicted the 3-month outcome were age, WFNF at admission, the modified Fischer score at admission, intraventricular hemorrhage, delayed cerebral ischemia, the level of IL-6, and the level of copeptin." (PMID 40508137, 2025).
ischemic cardiomyopathy (5 papers, 2018 to 2024). Ischemic cardiomyopathy is a cardiomyopathy in which a weakness in the muscle of the heart due to inadequate oxygen delivery to the myocardium with coronary artery disease being the most common cause. "Patients with non-ischemic cardiomyopathy had higher IL6 and TNFa levels prior to device implantation (Online resource 2)." (PMID 33078375, 2021). "Even in rats with established ischemic cardiomyopathy, physical training was able to restore the Treg population and mitigate the production of IL-6, TNF-α, and later IL-17 in peripheral blood." (PMID 30203627, 2018). "Further studies with HIF2α protein small molecule agonists should verify whether these molecules affect the cellular expression of IL-6 and reduce MIRI to provide a new target for the prevention and treatment of ischemic cardiomyopathy." (PMID 33428604, 2021). "Particularly, the levels of cytokines (e.g., IL-6, TNF-alpha) have been found higher in in patients with ischemic cardiomyopathy when compared with patients with non-ischemic cardiomyopathy." (PMID 35271674, 2022).
juvenile dermatomyositis (5 papers, 2015 to 2023). Juvenile dermatomyositis (JDM) is the early-onset form of dermatomyositis (DM), a systemic, autoimmune inflammatory muscle disorder, characterized by proximal muscle weakness, evocative skin lesion, and systemic manifestations. "Increased CD4+ cells, TH-17, IL-6, an expanded B cell population, and the emerging role of natural killer cells, as well as the PTPN22 R620W variant, are all linked to the increased risk of developing juvenile dermatomyositis." (PMID 34354904, 2021).
laryngeal squamous cell carcinoma (5 papers, 2018 to 2024). A squamous cell carcinoma that arises from the larynx. "In this study, it was also demonstrated that IL-1β-IL-6, and IL-8 are abnormally overexpressed in poorly differentiated laryngeal squamous cell carcinoma, indicating a significant difference compared to the control group." (PMID 38920620, 2024). "The hydro-alcoholic extract of oak in the human laryngeal epidermoid carcinoma (Hep-2) cells has strong anti-proliferative effects and reduces the production of interleukins (IL)-6 and IL-8 in the macrophage." (PMID 34466482, 2019). "One in vitro study showed that GPER1 is responsible for the upregulation of interleukin-6 (IL-6) and is thereby involved in promoting the proliferation and migration of laryngeal squamous cell carcinoma (LSCC) cells in response to bisphenol A, an estrogen mimetic." (PMID 38672656, 2024). "This activity could be mediated by ERs or GPER1 (G protein-coupled estrogen receptor 1), which was shown to trigger proliferation and migration in laryngeal squamous cell carcinoma (LaSCC) via Interleukin-6(IL-6) and signal transducer and activator of transcription 3 (STAT3)." (PMID 29498642, 2018).
lupus erythematosus (5 papers, 2021 to 2025). An autoimmune, connective tissue chronic inflammatory disorder affecting the skin, joints, kidneys, lungs, heart, and the peripheral blood cells. "The animal experiment found that the mice with lupus erythematosus had a reduced preference for sucrose along with significantly increased serum levels of IL-6 and interferon-γ, and downregulating Tas1r2 was observed in the mice with chronic colitis disease." (PMID 40090940, 2025). "In lupus erythematosus, IFNs, particularly IFN-κ and IFN-α, amplify inflammatory cascades in the skin characterized by cytokines such as IL-6, IL-1β, and TNF-α, and chemokines (CXCL9, CXCL10), resulting in sustained immune cell infiltration." (PMID 41479908, 2025).
Mitral regurgitation (5 papers, 2022 to 2024). An abnormality of the mitral valve characterized by insufficiency or incompetence of the mitral valve resulting in retrograde leaking of blood through the mitral valve upon ventricular contraction. "We reasoned that atrial dilation occurring in an overt pathological condition, such as mitral valve insufficiency, may represent a suitable clinical setting to test the hypothesis of a relationship between IL6 rise and HCN decrease." (PMID 39596280, 2024).
Mycobacterium infection (5 papers, 2010 to 2025). Infections with bacteria of the genus Mycobacterium. "Other pro-inflammatory cytokines such as TNF-α/IL-6 also engaged in limiting Mycobacterium infection." (PMID 36090984, 2022). "In addition, relative cytokine expression was evaluated for ifn-γ, ifn-β, and il-6, which participate in the control of mycobacterial infections and other bacterial infections." (PMID 35892656, 2022). "miR-99b upregulation has been observed to stimulate the production of proinflammatory cytokines such as IL-6, IL-12, IL-1β, and TNF-α in macrophages and DCs upon Mycobacterium infection." (PMID 27803700, 2016). "miR-146a modulates the inflammatory response upon Mycobacterium infection in Raw 264.7 cells by targeting IRAK1 and TRAF6, resulting in remarkably reduced translation of IL-6, IL-1β, and TNF-α." (PMID 27803700, 2016).
myeloid malignancies (5 papers, 2013 to 2023). "In keeping with these clinical findings, miR-146a KO mice have been shown to develop increased levels of pro-inflammatory cytokines such as IL-6 and TNFα and develop a myeloid malignancy that significantly reduces their lifespan." (PMID 36505238, 2022). "Importantly, reducing inflammation in miR-146a KO mice, by concomitant deletion of Tnf or Il6, has been shown to extend their lifespan by delaying the onset of myeloid malignancy." (PMID 36505238, 2022). "For example, increased production of IL6 by HSPCs, as a result of inflammation, rapidly induces HSC differentiation towards myeloid lineage (referred as myeloid skewing), a phenomenon often associated with age and other myeloid malignancies, such as MDS." (PMID 34439269, 2021). "In line with this, increasing studies are reporting elevated levels of cytokines, such as TNF, IFNs, IL-6, TGFβ, IL17 and IL-1, play a supporting role in disease maintenance, including MDS and other myeloid malignancies." (PMID 34439269, 2021).
myocardial disease (5 papers, 2019 to 2025). "In particular, increased IL-6 is a supposed culprit of myocardial disease and coagulopathy, which was observed in this case, although detailed mechanism is still obscure." (PMID 30944043, 2019).
myonecrosis (5 papers, 2015 to 2023). "This suggests that the increased plasma levels of IL-6, in the mdx/IL6 mice, can directly target skeletal muscle, altering muscle homeostasis and/or indirectly, stimulating the activity of factors that contribute to myonecrosis, increased inflammation and altered regenerative mechanisms." (PMID 26251044, 2015). "In the last experimental period examined (Day 7), the amount of myonecrosis, number of inflammatory cells, CD68+ (M1) and CD206+ (M2) macrophages as well as the expression of IL‐6, TNF‐α and TGF‐β mRNA were lower compared with previous periods (Day 2 and 4)." (PMID 30024093, 2018).
neurosarcoidosis (5 papers, 2013 to 2025). A sarcoidosis that involves the nervous system. "CSF concentration of IL-6 > 50 pg/mL was associated with a higher risk of relapse or progression of neurosarcoidosis." (PMID 33330556, 2020). "Another study reported increased IL-6 levels in the cerebrospinal fluid (CSF) of patients with neurosarcoidosis as compared to patients with multiple sclerosis or other inflammatory disorders." (PMID 33330556, 2020).